IL17A (interleukin 17A)
Diseases named in the same sentence as IL17A in open-access papers (continued):
Sharing a sentence is not in itself a finding about the gene and the disease.
autoimmune disease (continued). "Taken together, these data indicate that further studies are required to clearly understand the role of IL-17A in the pathogenesis of autoimmune diseases." (PMID 33132897, 2020). "IL-17A is a signature of a key T helper cell population and evidence suggests a crucial role for IL-17A in the pathogenesis of autoimmune diseases and neurodegenerative diseases." (PMID 33132897, 2020). "IL-17a (a member of the IL-17 family), in particular, is significant in autoimmune diseases and inflammatory processes." (PMID 32268527, 2020). "RORγt is necessary to induce the transcription of IL-17A, and some autoimmune diseases are dependent on Th17 cells." (PMID 30974919, 2019). "According to the literature, the increase of IL-17A was observed in autoimmune diseases such as rheumatoid arthritis, multiple sclerosis, systemic lupus erythematosus, and inflammatory bowel disease." (PMID 31468124, 2019). "Interleukin-17A (IL-17A) is a proinflammatory cytokine produced predominantly by CD4+ T-helper 17 cells as well as γδ T cells that play a potentially important role in autoimmune diseases." (PMID 30712132, 2019). "IL-17A blockade using anti-IL-17A monoclonal antibody shows therapeutic effects on autoimmune disease; however, the protein drug is much more costly than the small-molecule compound inhibitor." (PMID 31318609, 2019). "IL17A primarily binds to IL-17RA16 and initiates a pro-inflammatory signal, which is strongly involved in the progression of many autoimmune diseases in humans." (PMID 31776424, 2019). "This notion is further supported by recent evidence that secukinumab, a monoclonal antibody against IL‐17A, is effective in the treatment of ankylosing spondylitis, another IL‐17A–driven autoimmune disease." (PMID 30350355, 2019). "IL-17A production by γδ T cells has been involved in antifungal immunity and in the onset of autoimmune disease." (PMID 31572188, 2019). "These cells play a critical role in the pathogenesis of autoimmune diseases, leading to production of several cytokines as IL17A, IL22, IL21 and IL2614." (PMID 31776424, 2019). "The data showed that the verteporfin treatment preferentially inhibited IL-17A overproduction in all 3 autoimmune disease models." (PMID 31318609, 2019). "In several autoimmune diseases, human clinical trials with humanized neutralizing IL-17A antibodies have yielded encouraging results." (PMID 31803028, 2019). "Previous studies have shown that neutrophils can produce IL-17a in inflammatory and autoimmune diseases." (PMID 30616627, 2019). "For the conversion from a pro-inflammatory IL-17A-producing memory CCR6+ Th cell to a regulating cell to be functional in suppressing autoimmune diseases, the cells should migrate toward the site of inflammation." (PMID 31379807, 2019). "Of special interest is interleukin 17A (IL-17A), whose expression is reported to be elevated in autoimmune diseases." (PMID 31159823, 2019). "Our findings suggest that GLK-induced AhR–ROR-γt complex is a biomarker and therapeutic target for IL-17A–mediated autoimmune disease." (PMID 31318609, 2019). "These cells are the major source of pathogenic cytokines, including IL-17A, IFN-γ, and GM-CSF, which amplify CNS inflammation in autoimmune disease." (PMID 30755603, 2019). "DUSP4-deficient mice display decreased T-cell-secreted IL-17A; DUSP4-deficient mice are resistant to autoimmune disease induction in the EAE model." (PMID 31766293, 2019). "JKAP-knockout mice display enhanced T-cell-secreted IFN-γ and IL-17A; JKAP-knockout mice are more susceptible to the autoimmune disease induction in the EAE model." (PMID 31766293, 2019). "IL-17A plays dual roles including protection host from bacterial and fungi infections, and participating in the autoimmunity diseases." (PMID 30555804, 2018). "Considering the complexity and diversity of the intestinal microflora in different autoimmune diseases, an IL-17A monoclonal antibody should be used with caution." (PMID 29892286, 2018).
autoimmune disease (continued). "IL-17A is a major proinflammatory cytokine enhanced in the sera of patients with autoimmune diseases." (PMID 30214937, 2018). "TH17 cells produce the effector cytokines IL-17A, IL-17F, IL-22, and GM-CSF to mediate pathological inflammation responsible for many types of autoimmune diseases; targeting TH17 cells is thus a potential treatment for these diseases." (PMID 30451821, 2018). "IL-17A, a prototype member of this family, is involved in the pathogenesis of allergies, autoimmune diseases, allograft transplantations, and malignancies." (PMID 30345318, 2018). "Although IL-25 (originally termed IL-17E) shares structural similarity with other IL-17 family members it acts in an opposing manner to IL-17A, by inducing a suite of Type 2 responses and preventing IL-17A-dependent autoimmune disease." (PMID 30238872, 2018). "Interleukin 17A (IL-17) is a cytokine involved in the development of many autoimmune diseases as well as in inflammatory conditions." (PMID 29435651, 2018). "Retinoic-acid-receptor-related orphan nuclear receptor γt (RORγt) controls the transcription of interleukin-17A (IL-17A), which plays critical roles in the pathogenesis of autoimmune diseases." (PMID 30214937, 2018). "T cell–specific GLK transgenic mice spontaneously developed autoimmune diseases with selective induction of IL-17A in T cells." (PMID 30214937, 2018). "Vγ4 T cells have been reported to participate in autoimmune diseases and skin graft rejection at the early stages by producing IL-17A." (PMID 29915573, 2018). "The involvement of Th17 cells in autoimmune diseases appears to be via promoting inflammation through the production of IL-17A in addition to IL-21 and IL-22." (PMID 29995930, 2018). "IL-17A has emerged as a key player in the pathologies of inflammation, autoimmune disease, and immunity to microbes since its discovery two decades ago." (PMID 30409128, 2018). "As pro-inflammatory cells, Th17 cells can induce the occurrence of asthma and autoimmune diseases by secreting inflammatory factors such as IL-17A, IL-17F, IL-6 and tumor necrosis factor-α." (PMID 30089474, 2018). "Clinical evidence for the efficacy of IL-17A inhibition by biologic agents was initially shown in patients with chronic plaque psoriasis, another autoimmune disease mediated by the IL-17 pathway." (PMID 28270233, 2017). "IL-17A has recently emerged as an attractive target, especially for the treatment of T cell-mediated autoimmune diseases." (PMID 29403160, 2017). "In autoimmune diseases such as collagen-induced arthritis, a γδ T subset, Vγ4/Vδ4+ cells also potently produce IL-17A, exacerbating the disease." (PMID 28377603, 2017). "IL-17A plays a more important role in autoimmune diseases than IL-17F, and is a cytokine with a strong pro-inflammatory action." (PMID 28912678, 2017). "Recent reports suggest that Th17 cells, which produce IL-17A, IL-17 F, IL-21 and IL-22, not only mediate the clearance of pathogens but also promote the progression of tissue inflammation and autoimmune diseases." (PMID 28646856, 2017). "The roles of IL-17-family cytokines, especially IL-17A, in autoimmune diseases, allergic diseases and host defense against infection have gained extensive research." (PMID 28145881, 2017). "Functionally, the IL-23/IL-17A axis plays an important role in the development of inflammation and autoimmune diseases, and is becoming a potential therapeutic target for the treatment of these conditions." (PMID 28377603, 2017). "This subtype is involved in the pathological process of tumors, host defence, infection, autoimmune diseases, and transplant rejection through the secretion of certain cytokines, such as interleukin (IL)-17A, IL-17F, IL-21, IL-22, and IL-6." (PMID 28796055, 2017). "IFN-γ producing Th1 cells and IL-17A producing Th17 cells are very critical to autoimmune disease by inducing inflammation." (PMID 28095433, 2017).
autoimmune disease (continued). "Th17 cells and IL-17A play important roles in autoimmune diseases, chronic inflammatory diseases, infectious diseases and cancers." (PMID 28030850, 2017). "Similar observations have been made in various inflammatory and autoimmune diseases providing the rationale for development of the anti-IL-17A monoclonal antibody." (PMID 28491102, 2017). "IL-17A exerts diverse functions in promoting host defense against infection and contributes to autoimmune diseases including multiple sclerosis and rheumatoid arthritis." (PMID 28035060, 2017). "Meanwhile, IL-17A is confirmed to be elevated in autoimmune disorders including rheumatoid arthritis and multiple sclerosis, which accelerates disease progression through the induced inflammation." (PMID 28035060, 2017). "In this study, we observed an elevated TH17 cell frequency as well as elevated RORC- and IL-17A-mRNA expression in peripheral blood of overweight children without allergic asthma, allergic rhinoconjunctivitis, atopic dermatitis, or autoimmune disease." (PMID 29201026, 2017). "Further, double negative T cells are already well known for their ability to produce pathological IL-17A in the autoimmune disease systemic lupus erythrematous." (PMID 27658195, 2016). "MS is an inflammatory and demyelinating disorder of the central nerve system (CNS), and current studies have found that both Th1 and interleukin-17A (IL-17A)-secreting CD4 (Th17) lymphocytes are involved in the pathogenesis of this autoimmune disease." (PMID 27809910, 2016). "IL-17A and IL-17F, produced mainly by Th17 cells, have been found to be involved in the pathogenesis of autoimmune diseases including diabetes and chronic inflammation, such as periodontitis." (PMID 26924897, 2016). "Of particular interest is IL-17A, which is produced primarily by Th17 cells and contributes widely to inflammation and the severity of clinical symptoms in autoimmune diseases like MS and other inflammatory diseases." (PMID 27733178, 2016). "It has been proposed that Th17 plays crucial roles in the pathogenesis of proinflammatory disorders including autoimmune diseases via the production of IL-17A." (PMID 27820818, 2016). "IL-17A is the most investigated cytokine from this family, having a pro-inflammatory role in microbial infections, autoimmune diseases, metabolic disorders and cancer." (PMID 27506675, 2016). "Patients in those autoimmune diseases often have elevated levels of IL-17A and IL-17F in blood or affected tissues." (PMID 27308096, 2016). "We identified four compounds with robust inhibition on RORγt activity as well as on the expression of IL-17A and IL-17 F, indicating the potential utility of these compounds in the therapy of autoimmune diseases." (PMID 26021566, 2015). "Recently, studies have elucidated a potential treatment for autoimmune diseases by suppressing IL-17A and IL-17 F production using RORγt inhibitors." (PMID 26021566, 2015). "Overall, IL-17A exerts a wide range of functions in autoimmune diseases, host defense, transplantation, allergy, and malignancy." (PMID 26146463, 2015). "The current studies demonstrated that IL-17A plays an important role as a proinflammatory cytokine in autoimmune diseases and in chronic inflammatory diseases such as rheumatoid arthritis." (PMID 26839464, 2015). "IL-17A can mobilize, recruit, and activate neutrophils, leading to massive tissue inflammation, and promote the progression of autoimmune disease." (PMID 26504859, 2015). "In support of this view, targeting IL-23 pathway, IL-17 production or action by using IL-17R antagonist and IL-17A-blocking antibodies have been shown to attenuate autoimmune diseases." (PMID 26236331, 2015). "These classes of drugs are of growing importance as a therapeutical approach in inflammatory and autoimmune diseases such as RA by regulating IL-17A, IL-22, and IFN-γ levels, but with a few significant cardiovascular side effects." (PMID 26252209, 2015).
autoimmune disease (continued). "In recent years, IL-17A (IL-17), a pro-inflammatory cytokine, has received intense attention of researchers and clinicians alike with documented effects in inflammation and autoimmune diseases." (PMID 26236331, 2015). "AS is considered as an autoimmune disease and interleukin-17A (IL-17A-) producing Th17 cells are involved in AS pathogenesis." (PMID 26124839, 2015). "The cytokine interleukin (IL)-17A (referred to as IL-17) is produced mainly by T helper 17 cells (Th17) and constitutes the driving force in several autoimmune diseases." (PMID 25888974, 2015). "Th17 cells have a major role in autoimmune diseases thorough their involvement in development and differentiation of osteoblasts, and when enhanced by IL-23, they secrete, among other things, IL-17A and IL-17 F." (PMID 25510225, 2014). "IL-17A has been identified as a cytokine that contributes to inflammatory symptoms in autoimmune diseases." (PMID 24692552, 2014). "IL-17, the main product of this lymphocyte subset, plays an active role in inflammatory response and in autoimmune diseases and experimental studies displayed a neutrophil-mobilizing mechanism of IL-17A." (PMID 23379382, 2013). "Both IL-17A and IL-22 have been shown to be pro-inflammatory cytokines that participate in the pathogenesis of autoimmune diseases, such as rheumatoid arthritis (RA), Crohn’s disease, systemic lupus erythematosus (SLE), and psoriasis." (PMID 23874630, 2013). "Considering with these data from clinical trials for autoimmune disease, this hypothetical advantage for IL-17A inhibitors against asthma can be expected to have clinical benefits." (PMID 24032029, 2013). "Th17 cells have been implicated in host defense, inflammatory disease, tumorigenesis, autoimmune diseases, and transplant rejection, all of which are mediated by the production of several cytokines, including IL-17A, IL-17F, IL-21, and IL-22." (PMID 24223606, 2013). "The significance of IL-17A production by innate immune cells in host defense against infection as well as development of autoimmune diseases has been demonstrated and reviewed." (PMID 23956759, 2013). "Some clinical trials targeted at IL-17A have conducted and substantiated importance of IL-17A in autoimmune disorders." (PMID 24032029, 2013). "The compound also enhanced PPARγ mRNA expression indicating this new compound as promisor in inflammatory and autoimmune diseases treatment, mainly by reducing IL-17A levels in RA cells." (PMID 24078927, 2013). "The finding that IL-6 is coproduced by Th17 cells is in line with the finding that IL-17A promotes IL-6 secretion and underpins the general synergistic correlation between IL-6 and IL-17 in autoimmune diseases." (PMID 24155968, 2013). "We used IL-17A reporter mice to assess IL-17A expression in resting mice and during models of bacterial pneumonia and autoimmune disease." (PMID 22768117, 2012). "This strongly suggests that the currently generated anti-IL-17A aptamer has potent therapeutic potential for human autoimmune diseases." (PMID 22487172, 2012). "Studies with knockout mice and neutralizing antibodies have revealed a role for IL-17A in immunity to various bacterial and fungal infections and also in the induction and propagation of several autoimmune diseases." (PMID 22768117, 2012). "Interleukin 17 (IL-17), also known as IL-17A, plays an important role in tissue inflammation, and is involved in the pathophysiology of autoimmune diseases and organ allograft rejection." (PMID 22028838, 2011). "Seminal findings regarding TH17 cell populations that secrete predominantly interleukin (IL)-17A have been shown to play an important role in an increasing number of autoimmune diseases, including SS." (PMID 21182786, 2010). "Our results suggest that the activation of chronic inflammation, including the IL-17A mediated pathway, a signature of autoimmune diseases such as multiple sclerosis, is also critical in ALS." (PMID 21062492, 2010).
autoimmune disease (continued). "Given the important role that IL-17A plays in autoimmune diseases of the CNS, it is important to understand responses of CNS cells to IL-17RA signaling." (PMID 19400960, 2009). "In general, the proinflammatory role of IL-17A in autoimmune diseases is widely recognized." (PMID 40536951, 2026). "Additionally, we discuss the action of the new therapeutic antibody, which targets IL-17A and IL-17F, and the consequences of blocking IL-17F with respect to the gut microbiome and autoimmune diseases." (PMID 41142785, 2025). "Notably, RORγt-expressing ILC3s serve as key innate producers of interleukin-17A (IL-17A) and IL-22, which are crucial for modulating immune responses against extracellular bacteria and autoimmune diseases." (PMID 40585371, 2025). "Indeed, IL-17A is a key mediator of tissue inflammation in various autoimmune diseases and transplantation." (PMID 40534856, 2025). "However, under pathological conditions such as autoimmune diseases, the synergy between IL-17A and other pro-inflammatory cytokines – including TNF, IL-1, and IFN-γ – amplifies inflammatory responses, ultimately leading to tissue damage." (PMID 40469524, 2025). "This led us to a hypothesis explaining the paradox of inducing autoimmunity by TNF-blockade in context with IL-17-mediated autoimmune diseases and an explanation why VKHD should be treated with anti-IL-17A/F rather than with anti-TNF-α." (PMID 41142785, 2025). "Since IL-17A plays an effective role in the treatment of autoimmune diseases, hypertensive diseases, and tumor suppression, targeting it may have multiple protective effects in clinical therapy." (PMID 40028265, 2025). "IL-17A has already been implicated in the pathogenesis of various autoimmune diseases including rheumatoid arthritis (RA) and systemic lupus erythematosus (SLE) where increased serum and tissue levels of IL-17A have been found, and higher serum levels correlated with disease activity in patients." (PMID 38674039, 2024). "However, since 2015, the Food and Drug Administration (FDA) has authorized the use of IL‐17A‐targeting monoclonal antibodies for autoimmune diseases including psoriatic arthritis, plaque psoriasis, and ankylosing spondylitis." (PMID 38585232, 2024). "This raises the question of whether the patients’ autoimmune disease could be ameliorated by IL-17A inhibition (e.g., secukinumab), which remains to be ascertained." (PMID 39359478, 2024). "IL-17A plays a key role in the development and progression of autoimmune diseases." (PMID 39063202, 2024). "Th17 cells, with their IL‐17A secretion, were central players in autoimmune disease research." (PMID 38801403, 2024). "The evaluated cytokines can be classified into three broad groups: the proinflammatory Th-1 cytokines: IL-2, IFN-γ, and TNF-α; the counterbalancing Th-2 cytokines: IL-4, IL-5, IL-10, and IL-13; and the Th-17 cytokine IL-17A, which is actively involved in several autoimmune diseases including MS." (PMID 38932415, 2024). "Consequently, IL-17A, also recognized as IL-17, has garnered substantial interest due to its pro-inflammatory characteristics and involvement in autoimmune disorders." (PMID 39311381, 2024). "Currently, some anti-IL-17A (secukinumab, ixekizumab, bimekizumab, brodalumab, etc.)and anti-IL-23A (ustekinumab) monoclonal antibodies are used for the treatment of different autoimmune disorders including IBD, ulcerative colitis, psoriasis arthritis, rheumatoid arthritis, etc.52,53." (PMID 38956309, 2024). "Additionally, Th17 cells (IL-17A, IL-17F, IL-21, and IL-22) are known to play an inflammatory role in mediating autoimmune diseases.." (PMID 38685091, 2024). "IL-17A is the signature cytokine of the IL-17 cytokine family, mainly produced by CD4+ T (Th17) cells, and has not only been implicated in humans for host protective immunity against various pathogens but also in tissue inflammation and autoimmune diseases." (PMID 38792803, 2024).